SRRM2 (serine/arginine repetitive matrix 2)
Diseases named in the same sentence as SRRM2 in open-access papers (continued):
Sharing a sentence is not in itself a finding about the gene and the disease.
cancer (8 papers, 2012 to 2024). A tumor composed of atypical neoplastic, often pleomorphic cells that invade other tissues. "We concluded that SRRM2 is present on the surface of cancer-derived EVs and, hence, constitutes a marker for detection of cancer-derived EVs and is, thus, a potential diagnostic and prognostic circulating biomarker." (PMID 39329747, 2024). "In essence, even though classical IHC cannot define the precise subcellular localization of membrane-associated SRRM2, it is tempting to speculate that SRRM2 is exposed on the surface of primary cancer cells like it is on most cancer cell lines." (PMID 39329747, 2024). "Altogether, these experiments corroborated the specificity of EX-02 and, thus, the surface localization of SRRM2 on cancer cells." (PMID 39329747, 2024). "As such, our data warrant future investigations of the potential role of mislocalized intracellular proteins in general, and SRRM2 in particular, in the etiology and progression of cancer." (PMID 39329747, 2024). "The identification of SRRM2 on the surface of cancer cells was unexpected because the protein has thus far been identified as a key component of nuclear speckles." (PMID 39329747, 2024). "Yet, we unexpectedly observed that EX-02 also binds to living tumor cells, and additional investigations proved that SRRM2 is, indeed, exposed on the surface of cancer cells of different origin." (PMID 39329747, 2024). "Here, we describe the generation of an SRRM2-specific antibody using EVs derived from cancer cell lines for immunizations, demonstrating that SRRM2 is released from cancer cells via EVs." (PMID 39329747, 2024). "To obtain a first insight into the expression profile of surface-SRRM2 in vivo, we performed immunohistochemistry (IHC) on various types of primary cancer and corresponding adjacent tissues." (PMID 39329747, 2024). "Here, we used this antibody to demonstrate that SRRM2 is exposed on the surface of most cancer cell lines from various entities and, even more important, on cancer cells in vivo." (PMID 39329747, 2024). "From such an immunization, we unexpectedly obtained an antibody targeting the nuclear speckles protein SRRM2 and demonstrated that SRRM2 is exposed on the surface of most cancer cell lines investigated." (PMID 39329747, 2024). "Additionally, we show that SRRM2 is exposed on the surface of human cancer cells from different entities and constitutes a novel appealing cancer-associated target molecule, opening the way towards the development of novel SRRM2-targeting cancer therapies." (PMID 39329747, 2024). "Additionally, SRRM2 is also present on the surface of cancer-derived EVs, implicating the use of the protein as an attractive circulating biomarker for EV-based diagnostic approaches." (PMID 39329747, 2024). "Subsequent immunoblots with lysates from different cancer cell lines substantiated the assumed specificity of EX-02 as it gave a specific signal at approximately 300 kDa, corresponding to the expected size of SRRM2." (PMID 39329747, 2024). "Interestingly, the antibody also detected a minor band of approximately 200 kDa in size, pointing to the existence of different SRRM2 isoforms present in cancer cell lines at various ratios." (PMID 39329747, 2024). "SRRM2 has previously been detected in cancer-derived EVs by proteomic analysis." (PMID 39329747, 2024). "Due to these diverse staining patterns, it is tempting to speculate that different post-translationally modified isoforms of SRRM2 exist in cancer cells and that these modifications account for the divergent intracellular localizations of the protein." (PMID 39329747, 2024). "Collectively, we identified SRRM2 as a promising new target molecule exposed on the cancer cell surface and showed that our SRRM2-specific antibody can be used as a basis for the development of new targeted cancer therapies." (PMID 39329747, 2024). "Hence, surface SRRM2 is a new druggable (as demonstrated with CAR-T cells) target molecule on cancer cells." (PMID 39329747, 2024).
cancer (continued). "In this context, it is important to mention that SRRM2 is exposed on many permanent cancer cell lines and is absent from normal cells, at least those we investigated." (PMID 39329747, 2024). "Even more importantly, various primary cancer cells also reveal SRRM2 membrane staining, while in adjacent noncancer cells the protein mainly shows the expected nuclear staining." (PMID 39329747, 2024).
neurodevelopmental disorder (7 papers, 2023 to 2025). A behavioral and cognitive disorder with onset during the developmental period that involves impaired or aberrant development of intellectual, motor, or social functions. "While the present study focuses on the implications of SRRM2 mutations in neurodevelopmental disorders, previous research has demonstrated the importance of SRRM2 in embryonic development." (PMID 40046925, 2025). "Here, we document the rare case of a patient with neurodevelopmental disorder who presented with juvenile-onset tics associated with microdeletion of the SRRM2 gene." (PMID 40545495, 2025). "SRRM2-related neurodevelopmental disorder is a recently described genetic diagnosis caused by loss-of-function variants." (PMID 40545495, 2025). "We document the rare case of a 30-year-old man diagnosed with neurodevelopmental disorder and juvenile-onset tics associated with a microdeletion involving the SRRM2 gene." (PMID 40545495, 2025). "Despite these uncertainties, the consistent discovery of pathogenic mutations in SRRM2 highlights its role as a significant genetic factor in neurodevelopmental disorders." (PMID 40046925, 2025). "Currently, there are limited studies and reports on the association between SRRM2 and neurodevelopmental disorders." (PMID 40046925, 2025). "These mutations were associated with neurodevelopmental disorders and other phenotypes, highlighting the role of SRRM2 in neurodevelopmental processes." (PMID 40046925, 2025). "Our study reports a novel SRRM2 mutation (NM_016333: c.4661A > T, p.Q1554L), which was identified in a boy with neurodevelopmental disorders using WES and Sanger sequencing." (PMID 40046925, 2025). "Our description has enhanced the understanding of the phenotypic characteristics of SRRM2-related neurodevelopmental disorders and broaden the spectrum of pathogenic effects attributed to SRRM2 mutations." (PMID 40046925, 2025). "While SRRM2 is known to play a role in pre-mRNA splicing, the specific pathogenic mechanisms underlying the neurodevelopmental disorders observed in our study remain to be fully elucidated." (PMID 40046925, 2025). "SRRM2 is highly conserved throughout evolution and loss of function mutations in SRRM2 have been shown to cause neurodevelopmental disorders suggesting that perturbations leading to SRRM2 loss of function are deleterious to neurons." (PMID 36626563, 2023). "In this case, we report a neurodevelopmental disorder in a line that is caused by a nonsense mutation in SRRM2 (uc002crk.3; c.1415C>G; p.Ser472*)." (PMID 37621647, 2023). "In this study, we report a case of a patient with a neurodevelopmental disorder carrying a novel missense mutation in SRRM2 (NM_016333: c.4661A > T, p.Q1554L), whose various symptoms are consistent with other case reports of SRRM2-related neurodevelopmental disorders." (PMID 40046925, 2025). "We identified a novel pathogenic SRRM2 mutation in a patient with a neurodevelopmental disorder." (PMID 40046925, 2025). "More recently SRRM2 has been linked to neurodevelopmental disorders and inflammation." (PMID 40950074, 2025). "Previous studies have identified an enrichment of SRRM2 mutations in neurodevelopmental disorders." (PMID 40046925, 2025). "Loss of function mutations in the SRRM2 gene cause neurodevelopmental disorders." (PMID 40950074, 2025). "This is the first report of neurodevelopmental disorder caused by SRRM2 gene variant in a family." (PMID 37621647, 2023). "In conclusion, we have presented a rare case of SRRM2 gene microdeletion associated with juvenile-onset tics, widening the spectrum of neurodevelopmental disorders observed in the context of SRRM2 gene microdeletions." (PMID 40545495, 2025). "Our case report widens the spectrum of neurodevelopmental disorders observed in the context of SRRM2 gene microdeletions and prompts further research to disentangle the contributions of genetic and environmental factors to variable phenotypic expressions." (PMID 40545495, 2025).
neurodevelopmental disorder (continued). "The patient’s phenotype aligns closely with that of other reported patients with SRRM2-related neurodevelopmental disorders." (PMID 40046925, 2025). "Despite its critical role in cellular function, the association between SRRM2 and neurodevelopmental disorders is not well-understood." (PMID 40046925, 2025). "Dysfunction of SRRM2 has been connected to neurodevelopmental disorders." (PMID 37628788, 2023). "In addition to SRRM2 and PNN, we tested SETD1A—a histone methyltransferase implicated in neurodevelopmental disorders that contains 24 consecutive serines—and observed enrichment in tau aggregates." (PMID 36626563, 2023).
tumor (6 papers, 2020 to 2025). "We therefore consider surface SRRM2 a new druggable tumor-associated target molecule and EX-02 an attractive first-in-class candidate for the development of targeted therapies." (PMID 39329747, 2024). "Even more relevant, primary tumor cells also clearly reveal a membrane localization of SRRM2." (PMID 39329747, 2024). "Even though SRRM2 CAR-T cells were unable to eliminate the xenografted tumor cells completely, we observed that even a single injection of CAR-T cells showed a clear antitumor activity resulting in significant tumor growth delay." (PMID 39329747, 2024).
infection (4 papers, 2016 to 2026). The state of being infected such as from the introduction of a foreign agent such as serum, vaccine, antigenic substance or organism. "Further study is needed to confirm the function of SRRM2 in SVA infection of host cells." (PMID 35154063, 2022). "Subsequently, we infected THP-1 depleted cells for SRRM2 and SON or control cells with HIV-1 and we fixed them at 48 hr post-infection for immunofluorescence." (PMID 41493399, 2026).
neurodegenerative disease (3 papers, 2022 to 2024). A disorder of the central nervous system characterized by gradual and progressive loss of neural tissue and neurologic function. "Tau aggregates are a hallmark of multiple neurodegenerative diseases and can contain RNAs and RNA-binding proteins, including serine/arginine repetitive matrix protein 2 (SRRM2) and pinin (PNN)." (PMID 36626563, 2023). "Because SRRM2 and nuclear speckle formation appear to be present throughout metazoans, model organisms like D. melanogaster and C. elegans could be useful in studying this link to neurodegenerative disease." (PMID 36203874, 2022).
neurological disease (2 papers, 2010 to 2023). "NSUN4 and SRRM2 are both involved in neurological disorders; in particular, SRRM2, a splicing factor, regulates ethanol-cue-induced memory in flies." (PMID 37217680, 2023). "SRRM2 transcript was 1.27 fold (p<0.05) upregulated in peripheral blood of PD patients versus healthy controls and was unchanged in the blood of neurological disease patients versus the healthy controls." (PMID 20161708, 2010).
SRRM2 also shares sentences with these, for which no sentence is quoted: Parkinson's (2 papers); alcoholic liver diseases (1); anaplastic astrocytoma (1); bladder cancer (1); colon adenocarcinoma (1); corticobasal degeneration (1); COVID-19 (1); diabetes (1); glioma (1); liver cancer (1); non-Hodgkin lymphoma (1); ovarian carcinoma (1); type 2 diabetes (1); urinary tract disorder (1); yolk sac tumor (1).